TXN (thioredoxin)
Diseases named in the same sentence as TXN in open-access papers (continued):
Sharing a sentence is not in itself a finding about the gene and the disease.
infection (continued). "RipAY preferentially bond to the plant cytoplasmic thioredoxin Trx-h5, whose expression is specifically induced during pathogen infection and the GGCT activity of RipAY was most efficiently stimulated by Trx-h5." (PMID 27489796, 2016). "Subsequent functional characterizations confirmed the importance of the NADPH-dependent glutathione and thioredoxin antioxidation systems to rice infection." (PMID 24475267, 2014). "This suggests GTR1 is involved in ameliorating extracellular plant host oxidative defenses, but the thioredoxin antioxidation system plays less of a role in neutralizing plant ROS during early infection." (PMID 24475267, 2014). "Previous work in our laboratory demonstrated that fungal anti-oxidative responses are essential for survival during tissue infection, and that fungal growth can be inhibited in vivo by targeting fungal thioredoxin." (PMID 23853581, 2013). "Although genes of this cluster were induced during oxidative stress, many of them, including thioredoxin (Ar15) and alternative oxidase (Ar81), showed repression during infection." (PMID 22427966, 2012). "The results of this study shed light on the coordinated immune defense function of IFN-γ and thioredoxin during diverse stress responses to infection and apoptotic stimuli." (PMID 18983687, 2008). "For instance, Pst_TTP1 targets the chloroplast thioredoxin TaTrx, inhibiting a pro-senescence signaling cascade (the TaTrx–TaSGR1 module) that would normally generate ROS and trigger protective cell death around the infection site." (PMID 41295188, 2025). "As many as 1180 genes were differentially expressed and the most down-regulated genes were further analyzed for their role in infection (a chitin deacetylase, a C6 TF, a laccase, two proteases, the succinate dehydrogenase MoSSADH, the acetyltransferase MoACT, and the thioredoxin MoTRX2)." (PMID 38252628, 2024). "In the earliest stages of infection, at 45 min, the enrichment analysis detected the term “response to chemical” which contained the stress-related catalase-encoding gene, CAT1, and the thioredoxin-encoding gene, TRR1." (PMID 38427950, 2024). "Salmonella expressing OmpR A136D, I138D or Y230D variants, which do not bind to thioredoxin but associate with RNA polymerase as well as cognate sensor kinase and DNA, are attenuated in an acute model of infection." (PMID 36266276, 2022). "Intriguingly, transcriptional analysis of several F. hepatica developmental stages showed that immature (21 days post-infection) flukes favour the thioredoxin-dependent antioxidant defence system instead of GST-based defence mechanisms, contrary to F. gigantica." (PMID 36112664, 2022). "In this study, we found that one of the most significant infection-induced E. piscicida genes, trxlp, could be secreted and translocated into the cytosol of host cells upon infection, showing a conserved crystal structure to the host thioredoxin protein." (PMID 31314784, 2019). "Overall, our data should aid in clarifying the redox modification mechanisms of the thioredoxin system utilized by L. monocytogenes to adapt to niche environments outside and inside the host with a view to pathogen infection control from the public health perspective." (PMID 28702378, 2017). "In addition, the effect of RNAi-mediated gene silencing of catalase, glutathione peroxidase, thioredoxin and protein oxidation resistance 1 in the control of infection with A. marginale was evaluated." (PMID 29258559, 2017). "Thioredoxin was thought to be important virulence factor induced during pathogens infection or might protect Phytophthora from plant counter defenses." (PMID 29250043, 2017). "The immunogenicity of thioredoxin and enolase proteins from several protozoa and helminths has been well-evaluated, and both proteins were considered as potential vaccine candidates against those pathogens' infection." (PMID 27803923, 2016).
infection (continued). "Also interesting are the decreased levels of TRXL (only after LCD infection), since human thioredoxin (TRX) related proteins are known to integrate signals and prevent apoptosis from ER, oxidative and mitochondrial stresses." (PMID 22039490, 2011). "Moreover, the increase in the abundance of the respiratory chain proteins agrees with ROS production and consequently with a marked increase in the expression of various antioxidant enzymes, including superoxide dismutase and thioredoxin, which was observed following the infection." (PMID 39242536, 2024). "Together, these findings suggest that the thioredoxin (Trx) ROS scavenging system may help the highly aggressive V. dahliae to respond to oxidative stress conditions imposed by plant defenses during colonization or at the time of infection." (PMID 33922492, 2021). "After 24 hours of infection, we observed changes in the expression of proteins that had oxidoreductase activity and proteins involved in oxidative stress protection, including 2,5-diketo-D-gluconic acid reductase, OsmC, Dps, flavodoxin and TrxA_1 (thioredoxin)." (PMID 27775027, 2016). "Similarly, evidence of increased expression of the antioxidant thioredoxin in the skin of pink salmon provided additional support of pro-tolerance mechanisms as overexpression of thioredoxin can protect from oxidative stress induced during infection or inflammation in mammals." (PMID 24628956, 2014). "Activities that were absolutely essential during acute infection, but dispensable during persistency, include cell wall synthesis, ubiquinone-dependent aerobic respiration, proton motive force-dependent ATP synthesis, translational accuracy, DNA repair, and thioredoxin-mediated redox balance." (PMID 22911873, 2012). "Therefore, thioredoxin induced by IFN-γ upon infection, stress, or immune triggers for Th1 immune response appears to act as a protective factor that maintains immune cell homeostasis through mechanisms involving ROS-scavenging, anti-apoptotic and cytokine-regulating functions." (PMID 18983687, 2008). "Overexpression of genes for the antioxidant enzymes SOD, CAT, GPX, GST, glutaredoxin (Grx), thioredoxin (Trx), and protein disulfide isomerase (PDI) was detected following the infection of mosquito cells with dengue virus." (PMID 40476361, 2025). "TXN-2 inhibits CSFV replication, and in the case of BVDV, it is downregulated by the virus during early infection." (PMID 39318471, 2024). "Three key proteins, including FLNA, TXN, and CYCS, were subjected to Western blot analysis at 0, 4, and 24 h post infection (hpi) to validate the iTRAQ process." (PMID 37264422, 2023). "The modules that were co-up-regulated in CD4 and CD8 cells after infection included IRF9, IRF7, PLCB3, CXCL3, and TXN, among others." (PMID 34603402, 2021). "Here, we identified the M. oryzae glutathione and thioredoxin antioxidation systems as important NADPH-requiring processes, essential for infection, whose gene expression is controlled by Tps1 in response to glucose." (PMID 24475267, 2014). "have thioredoxin and glutathione (GSH) systems that are thought to play a major role as antioxidants during blood stage infection." (PMID 19229315, 2009). "The P. brassicae secondary infection effectors identified by Perez-Lopez did not include the chitin recognition protein, alginate lyase, thioredoxin, or thaumatin family protein." (PMID 36532436, 2022). "Only four sera from individuals with a high intensity infection cross-reacted with this tag, whereas thioredoxin was not recognized by other infected individuals." (PMID 35073344, 2022). "Thioredoxin, thioredoxin-dependent peroxide reductase, BolA-like protein 2, glutamate–cysteine ligase, and cytosolic NADP-isocitrate dehydrogenase are all integral to the “oxidative stress” pathway which was found in the top 10 enriched pathways of the initial phase of infection." (PMID 38138142, 2023).
infection (continued). "The simultaneous silencing of three genes, catalase, glutathione peroxidase, and thioredoxin as well as the oxidation resistance 1 gene by RNAi apparently favoured the colonization of BME26 cells by A. marginale, suggesting that the antioxidant response might play a role in the control of infection." (PMID 29258559, 2017). "Statistical analysis here revealed no influence of age, sex, infection time, etiology, ALT, AST, total bilirubin, prothrombin time and AFP on thioredoxin in HCC patients (P > 0.05, respectively)." (PMID 25871387, 2015). "Moreover, we have shown that glutathione and thioredoxin genes are expressed in a glucose- and Tps1-dependent manner, thus suggesting how NADPH-requiring antioxidation might be regulated and fuelled as the fungus exploits available sources of glucose during infection." (PMID 24475267, 2014). "However, unlike Δgtr1 strains, rice cells infected with the thioredoxin mutants did not stain with DAB, suggesting this system does not significantly participate in neutralizing host ROS defenses during the early infection of rice epidermal cells." (PMID 24475267, 2014).
neurodegenerative disease (10 papers, 2008 to 2026). A disorder of the central nervous system characterized by gradual and progressive loss of neural tissue and neurologic function. "The thioredoxin (Trx) system plays a crucial role in regulating redox balance and cellular functions in response to redox signals and stress, which are implicated in cell survival in various conditions, including neurodegenerative diseases." (PMID 39199129, 2024). "In the case of neurodegenerative diseases, the thioredoxin system plays a key role in protecting neuronal cells from oxidative damage and maintaining neural system functions." (PMID 38685115, 2024). "(HO‐1), heat shock protein Hsp72, sirtuins and thioredoxin/thioredoxin reductase system are potential ways to prevent the development of neurodegenerative diseases." (PMID 38429903, 2024). "Similarly, thioredoxin is also investigated for its role in neurodegenerative diseases, where maintaining redox balance is crucial for neuronal cell survival." (PMID 38474110, 2024). "Interestingly, neuroprotective curcumin, by inducing Nrf2 and vitagenes including Hsp32 (HO-1/HMOX1), Hsp70 and thioredoxin system and by inhibiting NF-κB activation, prevents neurodegenerative diseases." (PMID 32046944, 2020). "Additionally, preclinical evidence indicates that curcumin exerts neuroprotective effects in neurodegenerative diseases by upregulating antioxidant systems, such as Hsp70s, HO-1, and thioredoxin, which are essential for maintaining mitochondrial ROS homeostasis." (PMID 41562846, 2026). "Thioredoxin-TXNIP is a major regulator of mitochondrial-mediated oxidative stress in many pathologies including cerebrovascular and neurodegenerative diseases." (PMID 30670947, 2018).
kidney diseases (6 papers, 2017 to 2024). "We previously synthesized an albumin–thioredoxin fusion protein (Alb–Trx), which has a longer plasma half-life than thioredoxin, and reported its effectiveness in the treatment of respiratory and renal diseases." (PMID 37298708, 2023). "Therefore, our data suggest that inducing SIRT1, HO-1, and thioredoxin may have clinical therapeutic potential in kidney diseases under excessive ER stress conditions." (PMID 28146117, 2017).
cardiovascular diseases (5 papers, 2019 to 2024). "In cardiovascular diseases related to oxidative stress, reduced thioredoxin (Trx) scavenges ROS and exerts a protective effect to maintain cellular redox balance." (PMID 39125400, 2024). "Additionally, studies have suggested a potential role for thioredoxin in cardiovascular diseases, with its antioxidant properties possibly conferring protective effects." (PMID 38474110, 2024). "In cardiovascular diseases, alterations in the thioredoxin system may affect the oxidative stress response, inflammatory response, and endothelial function of cardiomyocytes, thereby participating in the formation of diseases such as atherosclerosis and myocardial infarction." (PMID 38685115, 2024). "Thioredoxin system is composed of the anti‐oxidant thioredoxin‐1 (TXN1), thioredoxin reductase (TXNRD1), thioredoxin peroxidase‐1 (PRDX1), and the pro‐oxidant thioredoxin‐interacting protein (TXINP), which functions as a crucial defense mechanism against oxidative damage in cardiovascular diseases." (PMID 32618439, 2020).
metabolic disease (3 papers, 2017 to 2025). A congenital disorder (due to inherited enzyme abnormality) or acquired (due to failure of a metabolically important organ) disorder resulting from an abnormal metabolic process. "The role of mitochondrial thioredoxin in mitochondrial function, lipolysis, and inflammation beyond NF-κB signaling should be investigated to understand metabolic disorders during transition periods in dairy cows." (PMID 41009046, 2025).
adenocarcinoma (2 papers, 2018 to 2025). A common cancer characterized by the presence of malignant glandular cells. "INS, TOP2A, ACACA, ALB, and TXN are the key genes which play an important role in adenocarcinoma." (PMID 30425814, 2018).
gastrointestinal disorders (1 paper, 2020). "Again, in our study, we did not examine the TXN genotype in our patients, but these new insights highlights the importance to investigate in future studies the status of the TXNB gene in patients with functional gastrointestinal disorders." (PMID 33259162, 2020).
respiratory diseases (1 paper, 2025). "Anti-oxidant activity of thioredoxin (Trx) was used to treat respiratory diseases with a fusion to HSA." (PMID 41020890, 2025).
TXN also shares sentences with these, for which no sentence is quoted: chronic kidney disease (3 papers); congestive heart failure (3); systemic lupus erythematosus (3); allergic bronchopulmonary aspergillosis (2); autism (2); autoimmune (2); Cognitive impairment (2); cystic fibrosis (2); diabetic neuropathy (2); ischemia reperfusion injury (2); kidney (2); Nephropathy (2); non-alcoholic fatty liver disease (2); Oral Squamous Cell Carcinoma (2); osteoarthritis (2); squamous cell carcinoma (2); viral pneumonia (2); abdominal aortic aneurysm (1); acute respiratory distress syndrome (1); African sleeping sickness (1); allergic rhinitis (1); amebic dysentery (1); ampullary carcinoma (1); Andersen-Tawil syndrome (1); ankylosing spondylitis (1); Anxiety (1); B-cell acute lymphoblastic leukemia (1); B-cell chronic lymphocytic leukemia (1); Bacterial Infections (1); Brain Diseases (1).
A further 64 diseases each share a sentence with TXN in 1 paper.